TNF (tumor necrosis factor)
Diseases named in the same sentence as TNF in open-access papers (continued):
Sharing a sentence is not in itself a finding about the gene and the disease.
ischemia (continued). "The tight BBB in our model could be disrupted by exposure to TNF-α and in conditions of ischemia." (PMID 26503597, 2015). "However, it is thought that transient ischemia-induced activation of NF-κB/p65 via toll like receptor 4 or 2 in glial cells would exert secondary injury to neurons by producing neuro-toxic cytokins such as TNFα and IL-1β." (PMID 24800741, 2014). "Moreover, increased serum c-TnI levels and myocardial leukocyte infiltration at early time-points postinjection and prolonged inflammatory responses indicated by increased myocardial TNF-α and IL 6 expression resembled typical inflammatory responses post-ischemia." (PMID 24137281, 2013). "TNFα and IL-1 have been shown to cause up-regulation of E-selectin, ICAM-1, ICAM-2, and VCAM-1 on cerebral endothelial cells and the induction of such adhesion molecules may explain the elevation of TNFα and IL-1 levels after ischemia increases neutrophil infiltration." (PMID 22196138, 2011). "In a rat model of permanent focal ischemia by embolisation of TiO2-spheres we assessed key features of post-ischemic neuroinflammation by the means of histology, immunocytochemistry of glial activation and influx of hematogeneous cells, and quantitative PCR of TNF-α, IL-1, IL-18, and iNOS mRNA." (PMID 21171972, 2010). "TLR4−/− mice and mice given LPS-RS, a TLR4 antagonist, exhibited decreased systemic IL6 and TNF-α levels after hindlimb ischemia, implicating the role of TLR4 in ischemia-induced systemic inflammatory cytokine production." (PMID 38510939, 2024). "This can be attributed to MCP-1′s ability to attract and recruit macrophages, which activates the downstream proteins TNF-alpha and VEGF, resulting in ischemia-induced neovascularization." (PMID 38279349, 2024). "After primary injury, glial cells and T cells are activated and inflammatory cytokines such as tumor necrosis factor-α (TNF-α) and interleukin-1-β (IL-1β) are released due to local inflammation, hematoma, and ischemia." (PMID 39246654, 2024). "Cytokines, namely, IL‐1β, TNF‐α, IL‐6 and IFN‐γ, rise 24 h post ischemia in a tMCAO model, and reducing the concentrations of these cytokines are highly advantageous to IS treatment." (PMID 37132060, 2023). "Our findings on cytokine kinetics are consistent with previous studies showing an increase of TNF-α, IL-6, and IL-8 within minutes after the start of surgery, changes being correlated with CPB and ischemia duration." (PMID 37522081, 2023). "Following ischemia, M1 are rapidly activated and release a variety of inflammatory mediators, such as IL-1 β, IL6, and TNF." (PMID 36598916, 2023). "Ischaemia led to a significant increase in MPO activity and TNF-α, and IL-6 concentrations in the ovaries when compared with the sham-operated animals." (PMID 36200598, 2022). "Many cytokines, including HIF-1, tumor necrosis factor (TNF), interleukins (ILs), and NF-κB, are involved in the inflammatory reactions in response to oxidative stress in ischemia." (PMID 36293053, 2022). "While percentage of IL10+ macrophages was unchanged, but percentages of TNF-α+ and IFN-γ+ macrophages were increased in PD-1-/- mice after hindlimb ischemia." (PMID 33815358, 2021). "Pioglitazone was found to inhibit TNFα-induced expression of ICAM-1 and VCAM-1 in activated cultured endothelial cells and an ischemia/reperfusion renal injury model." (PMID 34831270, 2021). "Increase in the serum concentration of proinflammatory cytokine tumor necrosis factor alpha (TNF-α) followed by the induction of vasodilatation leads to hypotension, ischemia, and kidney dysfunction." (PMID 34603243, 2021). "Elsewhere, administration of BBG decreased superoxide dismutase (SOD), malondialdehyde (MDA), TNF-α, and IL-1β concentration in pulmonary arterial hypertension (PAH) and ischemia-reperfusion- (IR-) induced lung models." (PMID 32566102, 2020).
ischemia (continued). "Moreover, as per our findings, ischemia led to an increase in the HDAC9 expression in the brain of wild type mice, while the loss of HDAC9 was observed to suppress the release of IL-1β, IL-6, IL-18, and TNF-α in the mouse cortex, hippocampus, and hypothalamus after I/R injury." (PMID 33584204, 2020). "In tissue harvested 24 hours after reperfusion, significant changes in gene expression were seen as early as after 1 hour of ischemia: PECAM-1 (3x), MUC1 (6x), and TNF-α (3x)." (PMID 31923917, 2020). "In the PEP-1 peptide-treated and control-PEBP1-trateed groups, MPO, TNF-α, and HMGB levels were significantly robustly increased in the spinal cord 72 h after ischemia compared to those in the control group." (PMID 31683736, 2019). "RT-qPCR showed that the expression levels of proinflammatory cytokines (IFN-γ, TNF-α, IL-1β) and the chemokine (MCP-1) mRNAs were significantly increased at 4 and 24 h after ischemia, and their increases were profoundly inhibited by CD147 inhibition." (PMID 31666088, 2019). "Our results indicate that rTMS reduces inflammation-related gene expression (IL1β, TNFα, MMP9, and TGFβ), as suggested using a pulsed electromagnetic field following ischemia." (PMID 31031599, 2019). "The most important inflammation related cytokines in brain during ischemia injury were IL-1, IL-6, COX-2, and TNF-α." (PMID 30854014, 2019). "While NADPH oxidase activity, MDA and TNF-α levels were significantly increased, SOD activity and GSH levels were reduced in ischemia and I/R groups." (PMID 30627370, 2018). "We detected the expression of mRNAs for various inflammatory cytokines (IL-1β, TNF-α, IL-6, IL-10, and TGF-β) in the cortex ipsilateral to sites of ischemia 24, 48, and 72 h after reperfusion." (PMID 27549161, 2016). "In the ischemia + PPG group, the TNF-α, IL-1β and IL-6 levels in the serum were significantly increased, the expression of ICAM-1 mRNA was increased, although without a significant difference, and the expression of NF-κB was increased." (PMID 25667680, 2015). "During myocardial ischaemia-reperfusion injury, L-THP administration significantly decreased the accumulation of inflammatory factors, including TNF-α and MPO." (PMID 26819501, 2015). "In the ischemia + PPG group, the serum levels of TNF-α, IL-1β and IL-6 were significantly increased compared with those in the ischemia group (P<0.05 or P<0.01)." (PMID 25667680, 2015). "Cytokines, such as interleukin (IL-6), IL-1β, and tumor necrosis factor-alpha (TNF-α), are detected in ischemic tissue as early as 3 hours after the onset of ischemia and are involved in later deleterious responses during cardiac remodeling." (PMID 25045207, 2014). "In animal model of acute lung inflammation induced by intestinal ischemia/reperfusion or LPS, LLLT has relieved airway inflammation through the induction of IL-10 and reduction of TNF and macrophage inflammatory protein-2 (MIP-2) expression." (PMID 24319484, 2013). "We further examined the expression of HIF-1α, TNF-α and IL1-β after ischemia and when treated with Melissa in the ischemic rat brain." (PMID 23351182, 2012). "Our results suggested that focal ischemia leads to proliferation of immature OLs in white matter and that TIMP-3 contributes to a caspase-3-dependent immature OL death via TNF-α-mediated neuroinflammation." (PMID 21871134, 2011). "In this study we have shown for the first time that in vitro organ culture of isolated cerebral arteries and in vivo ischemia models (MCAO and SAH) result in upregulation of TNF-α and TNF-α receptors after 48 h in cerebral vessels walls." (PMID 21871121, 2011). "Catecholamines, angiotensin II, tumor necrosis factor-alpha (TNF-alpha), tachycardia and ischemia induce generation of ROS in the myocardium." (PMID 26791643, 2011).
ischemia (continued). "Mechanical compressive ischemia was alleviated under the heat induced by warm needle acupuncture, which can also increase 6-keto-PGF1α, reduce hs-CRP, IL-6, and TNF-α levels, increase the content of endothelial growth factors, promote local revascularization, and reduce inflammation." (PMID 40860976, 2025). "After ischemia onset, microglia are rapidly activated to the M1 type along with GSK-3β overactivation and thus secrete a variety of proinflammatory factors, such as TNF-α, IL-1, and IL-6, leading to an inflammatory cascade." (PMID 41292262, 2025). "Blood samples collected pre‐ischemia and 24 h post‐reperfusion, along with muscle tissue samples after 24 h, demonstrated that EGb761 at 1000 μg/mL effectively inhibited IL‐6 and TNF‐α secretion in RAW 264.7 cells without cytotoxicity." (PMID 38839736, 2024). "During intestinal ischemia-reperfusion injury, MtDNA-STING signaling pathway promotes intestinal endothelial cell necrosis; in addition, mtDNA promotes the expression of IFN and TNF-α to induce intestinal necrosis." (PMID 38241222, 2024). "The interest in SSc has also been motivated by the possible role of TNF-α in potentiating the PAF (platelet activating factor)-induced vasoconstriction in the pulmonary circulation, since ischemia and reperfusion are major determinants of lung endothelial injury." (PMID 35629365, 2022). "The ischemia and pulmonary hypertension involved in APE can induce an increase in serum levels of cytokines and chemokines, including tumor necrosis factor-alpha (TNFα), interleukin (IL)-1β, IL-8, CX3CR1, CXCRL1, brain natriuretic peptide (BNP), troponin T (TnT) and D-dimer (D2D)." (PMID 35571119, 2022). "We also investigated whether cell/PEMF treatment affected the expression of the inflammatory intermediaries MMP-9, TNF-α, and IFN-γ in the mouse ischemia model." (PMID 35163096, 2022). "Studies have implied that inflammatory factors such as IL-6, TNF-α are targets of miRNA-149-5p, and the miRNA improves BBB function and integrity by reducing the mentioned factors following cerebral ischemia and decreases ischemia-reperfusion injury." (PMID 35871268, 2022). "The total number of TNF-α positive macrophages/muscle weight in PD-1-/- mice was significantly increased after hindlimb ischemia, but the percentage of TNF-α positive macrophages was not increased in PD-1-/- mice." (PMID 33815358, 2021). "In the present study, we analyzed the levels of TNF-α, IL-1β, and IL-6 in the hippocampus to validate the roles of Tat-SH3GL2 on ischemia-induced inflammatory responses because TNF-α promotes the migration of neurotrophils, IL-1β, and IL-6, which show pro-inflammatory roles." (PMID 33572372, 2021). "In a previous report after generalized ischemia, we indeed also observed that IL-6 was activated very early, whereas IL-1β or tumor necrosis factor-alpha were not." (PMID 33806919, 2021). "Moreover, magnesium isoglycyrrhizinate suppressed the levels of TNF-α, IL-1β, IL-6, antioxidant enzymes (SOD, GSHPx), iNOS, and caspase-3 in ischemia-reperfusion injury model rats." (PMID 34220502, 2021). "Our results indicate that ischemia of the adductor muscle significantly increased levels of TNF-α and IL-6 compared with the NONISCH (P < 0.05)." (PMID 33959422, 2021). "Additionally, propranolol was found to reduce TNFα and GFAP protein, among other inflammatory markers, in a rat model of ischemia." (PMID 34563566, 2021). "The splenic inflammatory response induced by cerebral ischemia was inhibited by αCD147 treatment as demonstrated by the reduced expression of cytokines (TNFα, IL-6, IL-1β) and monocyte chemoattractant protein-1 (MCP-1) in the spleen at 4 and 24 h after ischemia onset." (PMID 31666088, 2019).
ischemia (continued). "In accordance with the previous reports, our results showed increased inflammatory responses in a model of concurrent global ischemia superimposed on a model of aging in mice, while both PBM and/or CoQ10 partially, but significantly, attenuated the expression levels of TNF-α and IL-1β." (PMID 30983970, 2019). "Indeed, EP4 agonist significantly attenuated the production of TNFα, IL-6, IL-1β, and MCP-1 as well as macrophage infiltration in the heart after ischemia." (PMID 27190998, 2016). "Although both animal groups demonstrated similarly impaired learning after being subjected to the physiological stress of ischemia, the probe trial experiments showed that non-Tg rats had more accurate memory recall relative to TNFα-Tg rats." (PMID 27144978, 2016). "In addition, Hermann25 reported that TNF-α was released after SCI, which leads to central nervous system injury and secondary ischemia." (PMID 25686213, 2015). "The present study confirmed that IL-1β and TNF-α were induced by ischemia; however, IL-1β was downregulated in the serum of the GLGZD-2 group following treatment (P<0.05) and TNF-α was downregulated in the serum of the GLGZD-1 group following treatment (P<0.05)." (PMID 25815894, 2015). "Mild positivity of immunoreaction (tryptase, CD15, IL-1β, IL-6, IL-8, TNF-α) and stronger reactivity for IL-15, MCP-1 in areas where depletion of cellular antigens (myoglobin and cardiac troponin) is detectable within 30 – 40 minutes from ischemia." (PMID 24989171, 2014). "Using the pig intestine and T84 epithelial cell models, the aim of the present study was to investigate the effects of active linaclotide on barrier function and cellular changes induced by stressors such as ischemia in pig jejunum and IFN-γ and TNF-α, proinflammatory cytokines in T84 cells." (PMID 22553939, 2012). "TNF-α, TNF-R1 and TNF-R2 mRNA levels have been shown to increase in the brain after both permanent and transient MCAO in rat and mouse, and in neuroretina and retinal arteries following ischemia in pig and mouse." (PMID 21871121, 2011). "The present results also show that the TNF-α mRNA level in the neuroretina was significantly increased after ischemia and 5 h reperfusion, while after 12 h of reperfusion no significant increase was observed when compared to the sham-operated eyes." (PMID 21152396, 2010). "Collectively, these findings indicate that, within the studied range, neither the choice of cardioplegic solution nor the duration of ischemia had a statistically significant impact on the myocardial release of IL-4, IL-6, IL-10, leptin, TNF-α following ischemia/reperfusion injury." (PMID 40729334, 2025). "Therefore, TNF-α hindered axons regardless of NF-κB signaling in cultured cortical neurons after ischemia." (PMID 37676390, 2024). "In addition, we previously discovered that TNF-α mediates the interaction between microglia and double-negative T cells after ischemia, leading to aggravated brain injury." (PMID 37486903, 2023). "Based on this information, we studied pro-inflammatory (IL-6, TNF-alpha, and IL-1beta) and anti-inflammatory (IL-10 and TGF-beta) cytokines with ELISA to clarify whether there were any corresponding changes between them during different stages of ischemia." (PMID 37822799, 2023). "The complex regulation of the TNF gene and the lack of information about the behavior of this gene in clinical studies with ischemia, among others, might explain this finding." (PMID 35203700, 2022). "Spinal cord ischemia significantly increased the TNF-α levels in the spinal cord compared to that in the control group and administering PEP-1-PEBP1, not control-PEBP1, mitigated the ischemia-induced elevation of TNF-α levels in the spinal cord after ischemia/reperfusion." (PMID 31683736, 2019).
ischemia (continued). "We found that serum inflammatory cytokines, including IL-6, IL-1β, and TNF-α, were significantly decreased by MLB during hepatic ischemia/reperfusion (I/R) injury, suggesting that MLB may alleviate hepatic I/R injury via inhibiting inflammatory signaling pathways." (PMID 31231218, 2019). "In conclusion, the analysis of results demonstrates a clear increase in TNF-α and a decrease in CCL18 secretion by blood-derived monocytes from T2DM patients with diabetic foot syndrome in relation to carbohydrate metabolism status (compensated/decompensated) and the severity of ischemia." (PMID 31877847, 2019). "When evaluating ABI values in patients with long-term T2DM without foot ulcers we noted a significant increase in basal and stimulated TNF-α/CCL18 levels in all patients with chronic lower limb ischemia (ABI < 0.8) compared with patients without ischemia (ABI 0.9–1.2)." (PMID 31877847, 2019). "No BDNF+ cells were double labeled with TNF-α+ or IL-β+ cells in the brain, whether at the ischemia damaged areas or the intact areas." (PMID 30405724, 2018). "The confocal images showed that the expression of TNF-α and IL-1β in the activated microglia was significantly higher 24 h after the ischemic injury, compared to the sham-operated group, but it was markedly lower after treatment with LXW7 (compared to the ischemia group)." (PMID 27533766, 2016). "Finally, HDL failed to reduce IS in isolated hearts from TNF-α and STAT-3 deficient mice subjected to ischemia." (PMID 25237809, 2014). "Electrical stimulation of ST36 in rats with ischemia and reperfusion injury significantly blunted local gut cytokine levels, reduced the circulating serum levels of TNF-α and IL-8, decreased distant lung and liver levels of TNF-α and IL-8, which conduce to prevent SIRS or MODS." (PMID 23662144, 2013). "Within the first hours after onset of ischemia affected brain cells produce and secrete proinflammatory cytokines including monocyte chemoattractant protein-1 (MCP-1), interleukin-6 (IL-6), interleukin-1β (IL-1β), tumor necrosis factor-α (TNF-α) and granulocyte-colony stimulating factor (G-CSF)." (PMID 22031820, 2011). "Compared with the ischemia control group, the neurobehavioral scores, the infarction volumes, the apoptotic cells, the expressions and concentrations in brain tissue of TLR4, NFκB and TNFα were obviously decreased both in the picroside 2 and salvianic acid A sodium groups (P < 0.01)." (PMID 20618938, 2010). "Furthermore, endogenous zinc release was induced by cerebral ischaemia–reperfusion, resulting in increased expression of IL-1β, IL-6, TNFα, and the microglial M1 surface marker CD16/32, without hippocampal neuronal cell loss, in addition to impairments in object recognition memory." (PMID 28240322, 2017). "However, it does not appear that ischemia-dependent cognitive changes are worsened by TNF." (PMID 27144978, 2016). "The effect of expression of TNF-α in the brain cortex penumbra on infarction was evaluated by TTC staining in the non-DM and ischemia-treatment groups." (PMID 26665003, 2015). "In the HFD/RAPA 2-min TI group, IL-1β and TNF-α levels were significantly decreased (about 1.7-fold, p < 0.001, and 1.8-fold, p < 0.001 of the HFD 2-min TI group, respectively) at 2 days post-ischemia, and the decreased levels were not altered until 5 days post-ischemia." (PMID 31546722, 2019). "It is possible that the EPCs in patients with poor prognosis have a primary defect and do not respond to the stimuli of endothelial damage, ischemia add pressure overload, or that the EPC response is blunted by factors such as TNF-∞ that reduces the number of EPCs in these patients." (PMID 26913741, 2016). "In addition, HIF-1α+/+ hMSCs also attenuated the ischemia-induced inflammation characterized by massive infiltration of CD45-positive immune cells and elevated release of inflammatory cytokine TNF-α, which was not the case upon transplantation of HIF-1α−/− hMSCs." (PMID 37158785, 2024).
ischemia (continued). "However, microglial depletion raised the expression of TNF-α and MCP1 even without ischemia." (PMID 33757565, 2021). "However, we observed insignificant secretion of TNF-α and increased CCL18 in patients with foot ulcers and ischemia, while the basal (not stimulated) level of CCL18 was significantly higher in patients with foot ulcers (p < 0.027) compared to patients without foot ulcers." (PMID 31877847, 2019).